LGALS9 (galectin 9)
Diseases named in the same sentence as LGALS9 in open-access papers (continued):
Sharing a sentence is not in itself a finding about the gene and the disease.
pancreatic cancer (continued). "Furthermore, another study found that macrophage-expressed Dectin-1 can accelerate the progression of pancreatic cancer through ligation with galectin-9 in the tumor microenvironment, which depends on adaptive immunosuppression." (PMID 36131933, 2022). "Interestingly, in another study, it was also found that LGALS9 as the prognostic marker of pancreatic cancer was also enriched in RIG-I-like receptor signaling pathway and Cytosolic DNA-sensing pathway." (PMID 35898870, 2022). "The current review study identifies 22 IHC biomarkers as diagnostic tools for pancreatic cancer that embrace: Pentraxin-3, ENO1, REG4, POSTN, CA125, CA242, Galectin-1, Galectin-9, Maspin, pVHL, MUC1, MUC5AC, THBS2, LTBP2, CPA4, IMP3, CD13, Dkk1, KOC, S100P, Mesothelin, PAM4." (PMID 34988027, 2021). "Therefore, we are currently investigating other contributing factors of galectin-9 in the pancreatic tumor microenvironment." (PMID 32055023, 2020). "Given the importance of galectin-9 in anti-PD1 resistance and its role in pancreatic carcinogenesis, tolerogenic reprogramming and adaptive immune suppression targeting galectin-9 and PD-1 may be a promising strategy to unblock the immune response in pancreatic cancer." (PMID 38098486, 2023). "Notably, in pancreatic cancer cells galectin-9 has been shown to induce apoptosis." (PMID 32055023, 2020). "Similarly, to avoid the limitations of a single predictor, galectin-9 was included in a compelling immune biomarker panel to predict cancer-specific survival in pancreatic cancer, which might also benefit future prospective immunotherapy trials." (PMID 31832021, 2019). "Our single-cell ligand-receptor bubble plot analysis showed that in pancreatic cancer epithelial cells, the expression levels of MIF, MDK, and LGALS9 were significantly higher when NAT10 and KRT8 were highly expressed than when they were low-expressed." (PMID 41203621, 2025). "In another study using metastatic liver cancer cell lines derived from pancreatic cancer, including KMP2, KMP7, and KMP8, we demonstrated the in vitro antitumor effect of galectin-9 with apoptosis as the main mechanism." (PMID 37047155, 2023). "Mechanistically, dectin-1 binds to galectin-9, resulting in immunogenic or tolerogenic phenotypes of CD4 + and CD8 + T cells that promote tumour progression in pancreatic cancer." (PMID 31832021, 2019). "γδ T cells infiltrated in pancreatic cancer tissues can restrain CD4+ T cell and CD8+ T cell activation by expressing high levels of the immune check point proteins PD-L1 and Galectin-9, thereby negating adaptive anti-tumor immunity." (PMID 31064389, 2019). "Our meta-analysis supported the various function of different galectin subtypes in cancer prognosis, that converse to galectin-1, high levels of galectin-4 or galectin-9 predicted better OS and DFS in pancreatic cancer." (PMID 31832021, 2019). "Also, previous research found that serum galectin-9 is significantly higher in CLL patients as well as oral cancer, pancreatic cancer, and other hematologic malignancies." (PMID 37946029, 2024).
rheumatoid arthritis (32 papers, 2015 to 2025). A chronic, systemic autoimmune disorder characterized by inflammation in the synovial membranes and articular surfaces. "Our results suggest for the first time that genetic alterations in the LGALS9 gene are associated with rheumatoid arthritis in the Brazilian population." (PMID 31600237, 2019). "Therefore, this study was carried out to investigate the association of LGALS9 gene polymorphisms in Brazilian patients with rheumatoid arthritis." (PMID 31600237, 2019). "Based on the broad functions of galectin-9, we hypothesized that functional genetic polymorphism in the gene coding for galectin-9 (LGALS9) would be associated with susceptibility for rheumatoid arthritis." (PMID 31600237, 2019). "On the contrary, Xu’s group, investigating the association of LGALS9 polymorphisms with rheumatoid arthritis (RA), showed that rs4794976 allele T as well as TT and TT + TG genotypes were significantly associated with RA risk." (PMID 36768365, 2023). "There have been no reports regarding an association between rheumatoid arthritis and LGALS9 polymorphism, although galectin-9 has been shown to play an important role in RA pathophysiology." (PMID 31600237, 2019). "Galectin-9 (Gal-9) has been reported to directly modulate rheumatoid arthritis (RA) FLSs and to hold both pro- and anti-inflammatory properties." (PMID 36672263, 2023). "Of further interest in this context, two recent studies have reported galectin-9 as a valuable biomarker of disease activity in another TNF-driven disease – namely rheumatoid arthritis (RA)." (PMID 34276678, 2021). "As the AG genotype (rs3763959) has been associated with a higher presence of bone erosion in RA patients, these findings suggest that polymorphisms in LGALS9 may be an interesting aspect of rheumatoid arthritis for further exploration." (PMID 31600237, 2019). "Galectin-9 (Gal-9) is a mammalian lectin secreted by endothelial cells that is highly expressed in rheumatoid arthritis synovial tissues and synovial fluid." (PMID 29433546, 2018). "Galectin-9 (Gal9) has been postulated to have anti-inflammatory properties based on the ability of exogenous Gal9 to induce apoptosis in synovial fibroblasts in animal models of rheumatoid arthritis (RA)." (PMID 30150656, 2018). "This work proved that the presence of LGALS9, PTPRC and CD44 in platelets could serve as a clinical indicator of rheumatoid arthritis." (PMID 35563556, 2022). "In mammals, Galectin-9 could inhibit TLR7-mediated autoimmunity in murine lupus models and suppress the apoptosis in human rheumatoid arthritis synovial fibroblasts." (PMID 32362893, 2020). "The negative correlation between galectin-9 mRNA levels in peripheral blood mononuclear cells of patients with rheumatoid arthritis and the disease activity provides additional evidence that galectin-9 is anti-inflammatory." (PMID 28991189, 2017).
acute myeloid leukemia (31 papers, 2015 to 2025). Acute myeloid leukemia (AML) is a group of neoplasms arising from precursor cells committed to the myeloid cell-line differentiation. "This process triggers upregulation of galectin-9 expression in both malignant (mainly in breast and colorectal cancer as well as acute myeloid leukaemia (AML)) and embryonic cells." (PMID 33295886, 2020). "We have recently reported that the immune receptor Tim-3 and its natural ligand galectin-9 are involved in the immune escape of human acute myeloid leukemia (AML) cells." (PMID 31354733, 2019). "T-cell immunoglobulin mucin-3 (Tim-3), an inhibitory immune checkpoint receptor, is highly expressed on acute myeloid leukemia cells and its ligand galectin-9 is reported to drive leukemic progression by binding with Tim-3." (PMID 29179486, 2017). "Galectin-9 is increased in several hematologic neoplasia, including chronic lymphocytic leukemia, cutaneous T cell lymphoma, and acute myeloid leukemia (AML)." (PMID 38697976, 2024). "Recent studies showed that TIM-3 and galectin-9 interaction was involved in the immune escape of several malignancies such as acute myeloid leukemia (AML) and non-small cell lung cancer." (PMID 37347110, 2023). "In order to understand the ability of redox-dependent ASK1-mediated activation of AP-1 in TGF-β and galectin-9 production, we used THP-1 human acute myeloid leukaemia cells which express Toll-like receptor 4 (TLR4)." (PMID 33295886, 2020). "Acute myeloid leukemia cells (AMLs) express ADGRL1/LPHN1 (adhesion G protein-coupled receptor L1/latrophilin 1), which help to facilitate the secretion of galectin-9 (the immune suppressor that lacks a secretory domain) and TIM3 (T-cell immunoglobulin and mucin domain containing protein 3)." (PMID 35723340, 2022). "For example, the increased expression of CD200 and galectin-9 on cancer cells (ligands of CD200R and TIM-3 on NK cells, respectively) has been demonstrated in acute myeloid leukemia (AML)." (PMID 38254135, 2024).
gastric cancer (31 papers, 2013 to 2026). A primary or metastatic malignant neoplasm involving the stomach. "Galectin-9 has also been reported to be associated with gastric cancer." (PMID 37047155, 2023). "Functional experiments demonstrated that LGALS9 activation of P4HB promotes gastric cancer cell proliferation, EMT and expression of lipid metabolism genes." (PMID 40534096, 2025). "Our study is the first to identify P4HB as a functional receptor for LGALS9 in gastric cancer, establishing a novel signalling axis in the metastatic microenvironment." (PMID 40534096, 2025). "Galectin-9 expression has been shown to differ significantly between gastric cancer lesions and adjacent normal gastric mucosa, with most tumor cells exhibiting strong cytoplasmic Gal-9 immunoreactivity." (PMID 40710343, 2025). "Galectin-9 has demonstrated notable antitumor effects in gastric cancer cell lines, particularly by suppressing cellular proliferation and inducing apoptosis." (PMID 40710343, 2025). "Galectin-9 inhibits the proliferation of gastric cancer cell lines by altering miRNAs in vitro, mainly by inducing apoptosis." (PMID 37047155, 2023). "Immunohistochemical analysis showed that 86.2% of tumor tissues from gastric cancer patients were positive for galectin-9 and 60.0% for TIM-3." (PMID 37047155, 2023). "Both high expression of galectin-9 and low expression of TIM-3 were significantly associated with longer overall survival in gastric cancer patients." (PMID 37047155, 2023). "In this report, differentiation between extracellular and intracellular galectin-9 expression was complicated because it was performed by immunohistochemistry in human gastric cancer tissues." (PMID 37047155, 2023). "It has been reported that chemoradiotherapy increases the expression of galectin-9 and PD-L1 on the cell membrane in gastric cancer cell lines, and combination therapy in actual clinical practice is expected in the future." (PMID 37047155, 2023). "Cholangiocellular carcinoma, gallbladder cancer and gastric cancer are subject to galectin-9-induced apoptosis." (PMID 28045432, 2017). "For gastric cancer, the results seem controversial because the messenger RNA of galectin-9 decreased, while the protein expression increased compared with normal mucosa." (PMID 28045432, 2017). "Prognostically, high Galectin-9 expression is associated with longer survival in gastric cancer, yet marks T-cell exhaustion and poorer outcomes in non-small-cell lung cancer, underscoring the context-dependent nature of this lectin’s immune regulation." (PMID 40710343, 2025). "In another study, the galectin-9 positive group in gastric cancer tissues had significantly lower all-cause and gastric cancer-specific mortality rates than the galectin-9 negative group." (PMID 37047155, 2023). "A recent study also demonstrated that chemoradiation could induce increased expression of PD-L1 and LGALS9 in gastric cancer, however, whether similar result can be found in LC needs further study." (PMID 35311155, 2022). "Galectin-9 and Tim-3 expressions in gastric cancer according to clinicopathologic parameters." (PMID 24339967, 2013). "Violin plot analysis confirmed the expression of LGALS9 in myeloid cells and P4HB in epithelial cells across both metastatic sites, suggesting a conserved signalling mechanism in gastric cancer metastasis." (PMID 40534096, 2025). "Pharmacological inhibition of P4HB using Q3R or BAC effectively reversed the pro‐metastatic effects of LGALS9, suppressing proliferation, EMT and lipid metabolism in gastric cancer cells." (PMID 40534096, 2025). "In summary, this study combines transcriptomic analysis with ex vivo functional assays to uncover a role for Galectin-9 in promoting CD8+ T cell dysfunction and Treg expansion in gastric cancer." (PMID 40666515, 2025).
gastric cancer (continued). "Functional experiments confirmed that the activation of P4HB by LGALS9 significantly enhanced proliferation, epithelial‐mesenchymal transition (EMT) and lipid metabolism in gastric cancer cells, while pharmacological inhibition of P4HB reversed these effects." (PMID 40534096, 2025). "Galectin-9 has been widely implicated in CD8+ T cell exhaustion; however, its role in gastric cancer has not been previously characterized." (PMID 40666515, 2025). "Our analysis revealed that myeloid cell–derived Galectin‐9 (LGALS9) and its receptor beta‐subunit of prolyl 4‐hydroxylase (P4HB) on epithelial cells constitute a previously uncharacterized ligand–receptor interaction involved in gastric cancer metastasis." (PMID 40534096, 2025). "For a number of tumors, in particular for hepatocellular and colorectal carcinoma, the correlation of galectin-9 expression with better overall survival (OS), as well as with better progression-free survival (PFS) in gastric cancer (GC) and non-small cell lung cancer (NSCLC), was shown." (PMID 36140182, 2022). "Interestingly, simultaneous increases in the expressions of galectin-9, VISTA and Tim-3 were reported for other cancers, for example gastric cancer." (PMID 33329552, 2020). "Consistent with our transcriptomic findings, LGALS9 treatment upregulated the expression of genes involved in cholesterol metabolism (NPC2, APOA) and PPAR signalling (SCD, PLIN2, FABP1), suggesting that LGALS9‐P4HB interaction modulates lipid metabolism in gastric cancer cells." (PMID 40534096, 2025).
colon carcinoma (30 papers, 2015 to 2025). "In the present study, we found that galectin-9 expression was reduced in colon tumor tissues, which is associated with poor prognosis in these patients." (PMID 27028892, 2016). "A total of 90 colon cancer cases and their associate clinical and survival information were analyzed to determine the role of galectin-9 expression." (PMID 27028892, 2016). "We next investigated the infiltration of CD56+ NK cells in colon cancer tissues and its association with galectin-9 expression." (PMID 27028892, 2016). "Similarly, loss of Gal-9 via binding of the MiR-455-5p microRNA to the LGALS9 3′-untranslated region promoted colon cancer oncogenesis." (PMID 40869319, 2025). "Association between galectin-9 expression and clinicopathological features in colon cancer." (PMID 27028892, 2016). "Collectively, these results affirm that ATXN3 functions as a tumor suppressor by enhancing Galectin-9-induced colon cancer cell death." (PMID 38815863, 2024). "Intriguingly, ATXN3 acts as an endogenous deubiquitinase of Galectin-9, thereby targeting ATXN3 deletion resulting in the reduced Galectin-9 expression and apoptosis of colon cancer cells." (PMID 38815863, 2024). "Consistently, Galectin-9 treatment resulted in the elevated colon cancer cell death and inhibited their growth as documented by the increased cleaved caspase-3 positive cells and reduced ki67+ cells." (PMID 38815863, 2024). "Subsequent flow cytometry analysis corroborated a modest yet statistically significant reduction in the cell surface expression of Galectin-9 in colon cancer cells." (PMID 38815863, 2024). "Both ATXN3 and Galectin-9 protein expression levels exhibited a similar decrease in benign colon adenoma compared to colon adenocarcinoma, suggesting an early-stage involvement of ATXN3 and Galectin-9 reduction in colon cancer tumorigenesis." (PMID 38815863, 2024). "Surprisingly, our findings demonstrate that ATXN3 exerts an antitumor effect in human colon cancers through potentiating Galectin-9-induced apoptosis." (PMID 38815863, 2024). "Conversely, the treatment of mice with recombinant Galectin-9 significantly inhibited colon cancer growth." (PMID 38815863, 2024). "Nevertheless, the treatment of ATXN3 knockout colon cancer cells with the proteasomal inhibitor MG132 completely restored Galectin-9 protein expression." (PMID 38815863, 2024). "Consistently, the loss of ATXN3 functions significantly enhanced the colony formation of HCT116 and MC38 colon cancer cells, which was entirely reversed by the expression of Galectin-9." (PMID 38815863, 2024). "As expected, the stable expression of Galectin-9 completely neutralized the increased tumor growth induced by ATXN3 suppression, indicating that ATXN3 impedes colon cancer cell growth by stabilizing Galectin-9." (PMID 38815863, 2024). "Immunohistochemical staining revealed variable protein expression levels for both ATXN3 and Galectin-9 in colon cancers." (PMID 38815863, 2024). "Galectin-9 expression is downregulated in colon tumor tissues, and high expression of galectin-9 is associated with improved overall survival in colorectal cancer." (PMID 37047155, 2023). "In a mouse model using colon cancer cells, intravenous administration of galectin-9 reduced the number of metastases in the lung, suggesting that secreted Gal-9 suppresses metastasis." (PMID 37047155, 2023). "Galectin-9, a product of the LGALS9 gene, exerts a tumor-promoting activity in liver cancer, targeted by miR-22, and a tumor-restraining activity in colon cancer in which it is targeted by miR-455-5p." (PMID 36555445, 2022). "We showed that galectin-9 was expressed in 101 (78.91%) colon tumor tissues and that was expressed at lower levels in these tissues than in para-tumor tissues." (PMID 27028892, 2016). "First, we explored galectin-9 expression in colon cancer by analyzing 128 biopsies from colon tumors spanning stages I-IV according to TNM." (PMID 27028892, 2016).